APCDD1L (APC down-regulated 1 like)
Synonyms: FLJ90166
Tractability: Antibody: UniProt predicts a signal peptide or a membrane-spanning region; its Gene Ontology location is reachable by antibodies, with medium confidence.
Gene: Protein-coding gene on chromosome 20 (58,458,452 to 58,515,399, reverse strand). Ensembl gene ENSG00000198768.
Subcellular location: Membrane
Subcellular location (Human Protein Atlas): Mitochondria
Gene Ontology:
Molecular function: protein binding; Wnt-protein binding
Biological process: negative regulation of Wnt signaling pathway
Cellular component: membrane; plasma membrane
Genetic constraint (gnomAD): Loss-of-function variants: 21 observed, 15.29 expected, observed/expected ratio (o/e) 1.37, 90% interval 0.97 to 1.86. The synonymous counts are far from expectation, so gnomAD's model fits this gene poorly and the ratio says little. Missense variants: 704 observed, 615.58 expected, observed/expected ratio (o/e) 1.14, 90% interval 1.07 to 1.22. Synonymous variants: 321 observed, 264.05 expected, observed/expected ratio (o/e) 1.22, 90% interval 1.11 to 1.33.
Homologues: Orthologues: chimpanzee APCDD1L (99% identical), macaque APCDD1L (94% identical), dog APCDD1L (83% identical), pig APCDD1L (82% identical), tropical clawed frog apcdd1l (55% identical), rat Apcdd1l (53% identical), zebrafish apcdd1l (48% identical). Paralogues in human: APCDD1 (46% identical).
Diseases named in the same sentence as APCDD1L in open-access papers:
APCDD1L is named in the same sentence as 7 diseases in open-access papers, as found by Europe PMC text mining. Sharing a sentence is not in itself a finding about the gene and the disease. The quoted sentences say what the papers report.
rheumatoid arthritis (2 papers, 2021 to 2024). A chronic, systemic autoimmune disorder characterized by inflammation in the synovial membranes and articular surfaces. "Of the four remaining CpGs, according to the EWAS Catalog, one (cg23487201 at APCDD1L) has previously been associated with clear cell carcinoma and pancreatic ductal adenocarcinoma and another (cg00039564 at TAX1BP1) has previously been found to be associated with rheumatoid arthritis." (PMID 33517419, 2021).
breast carcinoma (1 paper, 2017). "During the treatments with veliparib and ponatinib, SNVs occurred on or near LATS1 (a core component of Hippo-YAP pathway), MGMT (related to DNA damage), IL17RB (related to NF-κB signaling) and APCDD1L (related to wnt signaling), all of which are known to be related to breast cancer." (PMID 29208983, 2017).
lung carcinoma (1 paper, 2022). "Single-cell transcriptomics of lung cancers reveals that SEC14L3 and APCDD1L were also enriched in monocyte." (PMID 36189290, 2022).
tumor (4 papers, 2018 to 2025). "TP63 has previously been shown to be expressed in the tumour cells in human ACP, but APCDD1L and BCL11B have not been implicated in ACP." (PMID 29541918, 2018).
APCDD1L also shares sentences with these, for which no sentence is quoted: cervical cancer (1 paper); clear cell carcinoma (1); pancreatic ductal adenocarcinoma (1).